EGFR (epidermal growth factor receptor)
Diseases named in the same sentence as EGFR in open-access papers (continued):
Sharing a sentence is not in itself a finding about the gene and the disease.
tumor (continued). "another emerging body of evidences indicates that intracellular circuitries involving tumor metabolism and immunogenic cell death are connected to the EGFR signaling pathway and, therefore, they might be also involved in the phenomenon of EGFR addiction." (PMID 23637683, 2013). "Combining an EGFR inhibitor with a B-Raf inhibitor has been shown to inhibit tumor growth in mice." (PMID 24276379, 2013). "EGFR-targeted therapy might then modulate (either increase or decrease) the addiction of tumor cells to other oncogenes." (PMID 23637683, 2013). "EGFR antibodies elicit both Fab- and Fc-mediated anti-tumour effects." (PMID 23918228, 2013). "The primary mechanism for activation of Stat3 in mouse keratinocytes exposed to tumor promoters is through activation of epidermal growth factor receptor (EGFR), although other pathways may also contribute to its activation during tumor promotion." (PMID 23577258, 2013). "These agents may inhibit tumor proliferation and promote tumor apoptosis via blockade of both mutant EGFR and Met signaling." (PMID 24386407, 2013). "Activating mutations in exon 19 of EGFR (delE746-A750) were unequivocally confirmed by PCR followed by FLA and by PNA–LNA PCR clamp techniques in three samples from CNS metastases and in a corresponding sample from a primary tumour." (PMID 23892415, 2013). "Vascular EGFR (VEGFR)-targeted therapies have been suggested to increase tumor invasiveness." (PMID 23496982, 2013). "In nearly all other tumor types, however, there does not appear to be a specific EGFR mutation that predicts for response to these therapies, and it has become clear that expression of the target alone does not suffice as a predictive biomarker." (PMID 24349829, 2013). "Also, to dissect out the benefit of anti-oxidant rich seaweed polyphenols in targeting tumor progression markers, first, we investigated the transcriptional regulation of Bcl2, EGFR, PDGFA, VEGF, AKT, TERT, kRas and FGF in PC cells." (PMID 23613993, 2013). "Activation of the EGFR signaling pathway results in increased tumor proliferation, angiogenesis, metastasis, and tumor invasiveness through the binding of a number of different ligands, including EGF-like molecules, transforming growth factor-α (TGFα), and neuregulins to the receptor’s ectodomain." (PMID 23824671, 2013). "In CRC, constitutively active KRAS mutation has been found to render tumor cells independent of EGFR signaling and thereby resistant to EGFR-targeted therapies." (PMID 23355875, 2013). "The correlations between clinicopathological features, including age, sex, pathological tumor stage, pathological lymph node stage, tumor differentiation, lymphatic vessel invasion (Ly), vascular invasion (V) and the gene amplification statuses of EGFR and HER2 and the DFS or OS were evaluated." (PMID 23426935, 2013). "The requirement of a higher glucose uptake by hypoxic tumor cells reinforces EGFR addiction." (PMID 23637683, 2013). "Furthermore, the expression of EGFR, VEGFR, and the phosphorylated receptors was observed on tumor-associated endothelial cells." (PMID 23986907, 2013). "The survival discrepancy between these two groups may have been the result of differences in pre-treatment variables and tumor responses to EGFR TKIs in these patients." (PMID 24376677, 2013). "seeMet 2 may be similar to the EGFR 806 antibody, that recognises a cryptic epitope that is only expressed on tumour cells." (PMID 23859937, 2013). "EGFR expression is frequently elevated in malignant breast cancers, including BLBCs, and such increased expression is thought to contribute to chemoresistance, aggressive growth and expression of tumour initiating ability." (PMID 23606532, 2013). "For such reasons, EGFR is an attractive target for tumor therapies." (PMID 23748900, 2013).
tumor (continued). "EGFR-targeted antibody therapy generates an anti-tumor T cell response." (PMID 23637683, 2013). "ALK fusion positive tumours are more common among non-smokers and the younger population, similar to those with EGFR mutations." (PMID 23289484, 2013). "The fact that dual silencing of EGFR and Rictor led to tumor eradication may suggest that such treatment targeted the BTICs." (PMID 23555046, 2013). "EGFR overexpression is correlated with advanced tumor stage and a poor clinical outcome." (PMID 24454509, 2013). "First, we tested whether LPEI could efficiently deliver EGFR-specific siRNA to the tumor site, leading to an antitumor effect in human NSCLC cell xenografts, when administered by intraperitoneal injection." (PMID 27234384, 2013). "Such a mechanism may partially contribute to the proliferation and growth of tumor cells with an LMP1-induced increase in the nuclear accumulation of EGFR and STAT3." (PMID 24499623, 2013). "Targeting TACE has been found to be a useful strategy in inflammation and EGFR-dependent tumours." (PMID 24027752, 2013). "Our 2 results suggest that EGFR-TKIs may improve cancer cachexia as a consequence of tumor shrinkage and suppress cancer related systemic inflammation." (PMID 23566546, 2013). "The activation of EGFR may contribute to the transformation of cellular phenotypes and provide tumor cells with substantial growth and survival advantages." (PMID 23555641, 2013). "EGFR mutation status was determined using the peptide nucleic acid-locked nucleic acid polymerase chain reaction clamp method, and immunohistochemistry was used to examine the expression of ERCC1 in tumor samples obtained from the patients." (PMID 23940741, 2013). "The determinants of tumor response and survival were assessed in patients treated with EGFR-TKIs." (PMID 23566546, 2013). "In contrast, cetuximab treatment did not cause any significant difference in tumor volumes induced by subclones that expressed low levels of EGFR." (PMID 23824671, 2013). "We speculate that chemotherapy may selectively kill and inhibit mutant clones within the tumor, whereas the clones exhibiting wild-type EGFR may proliferate abundantly following chemotherapy." (PMID 23520442, 2013). "Finally, tumours overexpressing cytoplasmic NHERF1 showed a significant trend with positive EGFR status (P = 0.053)." (PMID 23991686, 2013). "The discrepancies in survival benefits following EGFR TKI administration among NSCLC EGFR-mutant patients may result from both differences in pre-treatment variables and tumor response to treatment." (PMID 24376677, 2013). "Comparative analysis in 21 CRC samples of EGFR expression, between tumor and non malignant tissues, using two independent methods showed that somatic mutations of the EGFR polyA repeat did not result into an EGFR mRNA increase." (PMID 23565769, 2013). "In conclusion, results of the present study demonstrate that the EGFR expression levels, which were detected by cetuximab, may correlate with sensitivity to cetuximab-mediated inhibition of tumor cell growth." (PMID 23824671, 2013). "Here, we show that amplification and in particular activation of wild-type EGFR represents an underlying mechanism for non-angiogenic, invasive tumor growth." (PMID 23429996, 2013). "The upregulation of EGFR signaling within the tumor stroma deserves closer attention and may be a novel target for anticancer therapies." (PMID 23688423, 2013). "In contrast to the paradigm of other neoplasms, no activating mutations, such as EGFR or PI3K, are known to drive nasopharyngeal carcinogenesis." (PMID 23360534, 2013). "Coding sequence alterations of EGFR are frequently found in many types of human tumours." (PMID 24376686, 2013). "Translation of results from our study to the clinical setting suggests that inhibition of angiogenesis with EGFR antagonists may be better targeted at select tumours which are particularly hypoxic." (PMID 24180698, 2013).
tumor (continued). "Enhanced EGF receptor (EGFR) signaling is a hallmark of many human cancers, though the role of enhanced EGFR signaling within the surrounding tumor stroma has not been well studied." (PMID 23688423, 2013). "The H1299 EGFR tumor xenograft expressing EGFR represented a model of therapy-resistant tumors." (PMID 23956990, 2013). "Treatment with CH12, but not with cetuximab, of mice over-expressing the de4 EGFR variant significantly suppresses tumor proliferation and angiogenesis, leading to tumor apoptosis." (PMID 24285959, 2013). "When the KRAS mutant tumor cells were minority, most of KRAS wild-type tumor cells could also be killed by EGFR antibody treatment and in this process cancer patients could show a relatively long time of stable disease or even partial response." (PMID 23874486, 2013). "Of these agents gemcitabine exhibited the highest anti-proliferative activity with IC50 values at the low nanomolar range while afatinib with a range of IC50 values from 11nM to 1.37 μM demonstrated a higher anti-tumour activity compared to first generation EGFR TKI erlotinib." (PMID 23367880, 2013). "Due to potential crosstalk and a well-established role in tumor growth and angiogenesis, inhibition of both EGFR and VEGFR2 signaling may improve the clinical outcome of advanced NSCLC patients." (PMID 24124611, 2013). "Overexpression of EGFR is frequently found in various tumor entities." (PMID 24077122, 2013). "Wild-type EGFR expression, as compared to mock, increased tumor growth and Angptl4 expression in vivo, and also activated ERK phosphorylation in the LN229 cells; however, the degree of activation was not significantly different from that induced by EGFRvIII expression (data not shown)." (PMID 23617883, 2013). "Analysis of primary tumours in the remaining patients with EGFR mutation positive CNS metastases was not possible owing to lack of available tissue." (PMID 23892415, 2013). "However, the stem-like tumor cells used in their study expressed high levels of EGFR in contrast to the NCH644 and NCH421k cells." (PMID 24294177, 2013). "Notably, a significant fraction (>10 %) of moderate-to-high pEGFR positive tumor cells (score ≥ 4) was exclusively found in amplified tumors with high EGFR expression (score ≥ 4)." (PMID 23429996, 2013). "No mutations in exons 19 and 21 of the EGFR were observed in the 127 patient tumor samples using direct sequencing analysis." (PMID 24103528, 2013). "Consistent with the majority of clinical studies, experimental studies have also shown that the activation of the EGFR pathway was likely to be involved in the process of cancer metastasis, while EGFR overexpression promoted the metastasis of several types of tumor cells." (PMID 24137392, 2013). "A high expression level of EGFR was observed in the tumor cell membranes of control mice." (PMID 24191959, 2013). "Interestingly, IgA2 EGFR induced significant anti-tumour activity also in WT SCID mice in the A431 peritoneal model, indicating a contribution of Fab-mediated mechanisms to the anti-tumour effects." (PMID 23918228, 2013). "Other basal markers reportedly expressed in tumor cells include Bcl2, EGFR, and Met." (PMID 24199173, 2013). "However, EGFR McAb was able to block the EGFR and restrain tumor cell growth in a number of preclinical and clinical studies." (PMID 23833649, 2013). "In GC, EGFR overexpression correlates with advanced tumor stage and a poor clinical outcome." (PMID 23555641, 2013). "In addition, EGFR/HER1 correlated negatively to intra-tumour (r=-0.633, P=0.001) as well as normal tissue (r=-0.556, P=0.006) and plasma estradiol levels (r=-0.625, P=0.002), suggesting an inverse regulation between estradiol and EGFR/HER1 levels." (PMID 23991224, 2013). "Further, target antigens used to deliver TNF in these scFv-TNF fusion proteins are often not tumor specific but tumor associated or overexpressed, such as the Epidermal Growth Factor Receptor (EGFR) or Her2." (PMID 23840967, 2013).
tumor (continued). "In order to identify the best threshold values for the EGFR TMDA, we first analysed with this method a training set of 30 NSCLC and 6 CRC samples, which were included as negative controls due to the rare presence of EGFR mutations in this tumor type." (PMID 24364033, 2013). "As an approach to personalized therapy, the expression levels of both EGFR and Mig6 could be examined in tumor cells, and the ratio of the 2 molecules could be used to select patients who are likely to benefit from anti-EGFR therapy." (PMID 23935914, 2013). "Therefore, we have been investigated the new EGFR-TK imaging probes superior to PHY in tumor accumulation and retention by the ligand structure modification." (PMID 23494210, 2013). "In this context, the stabilizing effect exerted by the EGFR on the sodium/glucose co-transporters might contribute to reinforce the addiction of tumor cells to this oncogene." (PMID 23637683, 2013). "Thus, our findings suggest that 3H-FLT can reflect EGFR activation and can be a predictor of the tumor response to gefitinib in human tumor xenograft." (PMID 24191959, 2013). "Accordingly, our design of new EGFR-TK ligands for tumor diagnosis was appropriate." (PMID 23494210, 2013). "Furthermore, stimulation of EGFR pathways has been shown to promote tumour cell invasion, motility, adhesion and metastasis." (PMID 24180698, 2013). "We speculated that rapid tumor progression may occur in samples with a low percentage of EGFR mutant cells, owing to the fact that the apoptotic EGFR mutant cells responding to EGFR-TKI were outnumbered by proliferating non-mutant cells." (PMID 23418425, 2013). "In addition to the pronounced reduction of activated fibroblasts when AREG was silenced, we also noted changes in activation of the amphiregulin receptor EGFR (MIM: 131550) on tumor cells." (PMID 24068959, 2013). "Since, EGFR signaling is crucial for cell survival and proliferation; it might be the main reason for tumor progression in NSCLC." (PMID 23874428, 2013). "Based on these results, we propose a new model of EGFR testing in tumor and blood." (PMID 24039832, 2013). "FISH analysis was conducted on 85 tumor samples to measure EGFR copy numbers." (PMID 23418425, 2013). "Our data suggest that IGFBP3 and EGFR may share a common transcriptional hub or factory, and disruption of these interactions could play a role in tumor progression." (PMID 24019942, 2013). "While EGFR amplification may represent a small percentage of cells in the primary tumor, engraftment into rodents intracranially appears to select specifically for these cells for reasons that are currently not well understood." (PMID 24349039, 2013). "Additional factors may include crosstalk between IGFBP3 and EGFR signaling pathways and tumor heterogeneity." (PMID 24019942, 2013). "The real-time PCR analysis of EGFR and KRAS mutations conducted in the present study, led to identification of EGFR c.2582T>A (L861Q) and KRAS c.35G>T (G12V), detected in 1,000–5,000 and 100–1,000 tumor cells, respectively." (PMID 23817662, 2013). "Therefore, the effects of treatments on tumor profiling should be evaluated before making decisions regarding second- or third-line EGFR-TKI therapies for NSCLC patients." (PMID 23520442, 2013). "Furthermore, we showed that HGF overexpression is present in tumors from Japanese patients with acquired and intrinsic tumor resistance to EGFR-TKI at frequencies of about 60% and 30%, respectively." (PMID 23690929, 2013). "In addition, a recent lung cancer clinical trial showed that cetuximab can increase overall survival rate if the tumor shows EGFR overexpression." (PMID 23990977, 2013). "The present study indicates that fluorescently labeled anti-EGFR Affibody can provide significantly better delineation of tumor margins than a fluorescently labeled anti-EGFR antibody and shows considerable potential for guiding margin detection during neurosurgery." (PMID 23593208, 2013).
tumor (continued). "Second biopsy of EGFR-mutated tumor has been broadly recognized as necessary, but is not always performed in daily practice, mainly due to the imbalance between the potential risk of the diagnostic procedure and the therapeutic impact of the biopsy result." (PMID 24195468, 2013). "However, when monocytes were used in an overnight assay, marked tumour lysis was detected, which was higher by IgA2 EGFR than by cetuximab." (PMID 23918228, 2013). "Patient responses may by improved by administering a combination of EGFR-TKI therapy and other therapeutics capable of clearing non-EGFR mutant tumor cells in a simultaneous or sequential manner." (PMID 23418425, 2013). "Rare EGFR and KRAS mutations and tumor response to EGFR TKI." (PMID 23922984, 2013). "In the present study we showed that AnxA6 is indeed required for the sustained localization of activated EGFR on the surface of invasive tumor cells and that this contributes to persistent activation of downstream effectors that drive motility and invasiveness of the cells." (PMID 24354805, 2013). "As a first step in this direction, here we expressed a chimeric granzyme B fusion protein in human NK cells that carries the peptide ligand TGFα for targeting to EGFR, and evaluated its effect on natural cytotoxicity and its cell killing activity towards EGFR-expressing tumor cells." (PMID 23573299, 2013). "Surgical specimens can show relatively complete tumor genomics, thus avoiding or reducing false-negative results of EGFR mutation detections." (PMID 24351833, 2013). "Since EGFR signaling is crucial for the cell survival and proliferation, it might be the main reason for tumor progression in NSCLC." (PMID 23874428, 2013). "Thus, we further investigated the effect of estrogen and ERβ on the EGFR signaling pathway in suppression of tumor progression." (PMID 23460808, 2013). "Emerging clinical data suggest that intra-tumor let-7a expression correlates with tumor response and overall survival in metastatic colorectal cancer patients receiving epidermal growth factor (EGFR) targeting agents in both KRAS wild-type and mutant populations." (PMID 23936455, 2013). "In addition, microarray analysis of human HNSCC tumor samples showed that SphK1 expression correlates with genes downstream of the EGFR pathway in ESCC (i.e., amphiregulin, integrinα5, epiregulin)." (PMID 24970177, 2013). "Integration of the Shh and EGFR pathways could be a critical step in cancer initiation and/or tumor growth." (PMID 24133411, 2013). "In addition, it was reported that vorinostat, a pan-HDAC inhibitor, induces EGFR ubiquitination in tumor cell lines by predominantly targeting lysosome-degradation." (PMID 23342059, 2013). "The fact that the combined silencing of EGFR and Rictor led to tumor eradication may have been anticipated on the basis of previous publications which have demonstrated the involvement of both proteins in tumor progression." (PMID 23555046, 2013). "Moreover, the geraniin-dependent inhibition of Hsp90α chaperone activity caused a dose-dependent decrease in the level of the oncogenic proteins c-Raf, pAkt and EGFR, further supporting the potential of this compound to interfere with tumor progression." (PMID 24066128, 2013). "The EGFR-Ras-Raf pathway has a well-described role in skin development and tumor formation." (PMID 24071938, 2013). "Previous studies showed that EGFR mutations are more common in tumours from female patients, Asian origin, never-smoker and adenocarcinoma histology." (PMID 23590575, 2013). "Linear polyethylenimine (LPEI) is considered as a desirable gene in vivo delivery system, but whether it could deliver the specific siRNA targeted EGFR to the tumor site to inhibit the growth of NSCLC xenograft in nude mice still needs to be examined." (PMID 27234384, 2013). "However, when the endosomolytic reagent chloroquine was present, GrB-T from NKL/GrB-T supernatant efficiently killed EGFR-overexpressing tumor cells." (PMID 23573299, 2013).